BECN1 (beclin 1)
Diseases named in the same sentence as BECN1 in open-access papers (continued):
Sharing a sentence is not in itself a finding about the gene and the disease.
breast carcinoma (continued). "Monoallelic deletion of the BECN1 gene has been discovered in human prostate, ovarian, and breast cancers." (PMID 32121322, 2020). "Due to the genomic close proximity of the BRCA1 (breast cancer 1, early‐onset gene) and the BECN1 gene at the 17q21 chromosome, it was assumed that BECN1 deletions are rather a passenger event." (PMID 32935427, 2020). "Tumor generation was enhanced upon transplantation of Beclin 1-deleted adherent breast cancer cells, which supports the role of Beclin 1 as a general tumor suppressor." (PMID 32195258, 2020). "For example, in breast carcinoma cells, it negatively controls tumor progression by blocking autophagy induction of beclin-1." (PMID 31653087, 2019). "BECN1 was first known as a tumor suppressor in breast cancer and the expression of BECN1 was reported to be downregulated in many cancers." (PMID 31272261, 2019). "In MCF-7 breast cancer cells, BECN1 silencing was correlated to the corecruitment of G9a and DNMT1 on its promoter." (PMID 31861179, 2019). "Human BECN1 (Beclin 1 autophagy related gene) is located on chromosome 17q21, and monoallelic deletions of that region are found in up to 50% of breast cancers, 75% of ovarian cancers and 40% of prostate cancers." (PMID 31877888, 2019). "These mice show an increased susceptibility to tumor formation and an elevated incidence of lung carcinomas, lymphomas, hepatocellular carcinomas, and breast carcinomas, demonstrating the role of Beclin 1 in tumorigenesis." (PMID 31877888, 2019). "In breast cancer cell-lines, the overexpression of Beclin 1 intensifies the rate of autophagy and hinders the cellular tumorigenesis." (PMID 30717078, 2019). "In breast cancers, G9a expression was inversely correlated to BECN1 expression and patients with high G9a levels and low BECN1 expression presented the worst prognosis." (PMID 31861179, 2019). "Due to the close proximity of the BRCA1 (breast cancer 1, early onset) and the BECN1 gene at the 17q21 chromosome, it was postulated that BECN1 deletions are rather a passenger event." (PMID 31877888, 2019). "Autophagy markers, such as Beclin-1, LC3-II, lysosomal-associated membrane protein 1 (LAMP-1), and cathepsin-D, were upregulated in both breast cancer cell lines." (PMID 30654580, 2019). "Decreased Beclin 1 proteins have been reported in breast cancers compared to normal tissue, as well as in other cancer entities, such as ovarian carcinomas, colon cancer, non-small cell lung cancer, cholangiocarcinoma, gastric cancer, and renal cell carcinoma." (PMID 31877888, 2019). "Accordingly, recent evidence earmark NHERF1 as an autophagy regulator in breast cancers via its influence on the ubiquitin-dependent degradation of BECN1, a critical component of the autophagic core lipid kinase complex." (PMID 29551770, 2018). "In a recent work, carnosol, a naturally occurring compound is reported to block cell cycle at G2 phase and also found to increase ROS-dependent apoptosis and beclin-1-independent autophagy in triple-negative MDA-MB-231 human breast cancer cells." (PMID 29681985, 2018). "For example, a previous study showed that allelic loss of autophagy gene, Beclin 1, increases the risk of patients developing the aggressive HER2-positive breast cancer." (PMID 30018246, 2018). "In EGFR/HER2-inhibitor resistant breast cancer cells, there is enhanced autophagy in response to the inhibitor, which can be switched to apoptosis by BECN1 depletion." (PMID 30370269, 2018). "Breast cancer cells showed Beclin-1 and LC3B immunoreactivity and widened perinuclear cisterna, induced by stress depending atorvastatin treatment." (PMID 29485098, 2018). "In our study, we have observed that the protein expression of Beclin 1 level in TAM-resistant breast cancer cells is higher than parental breast cancer cells after long-term exposure to TAM." (PMID 28881721, 2017).
breast carcinoma (continued). "Upregulation of miR-20a strongly associates with downregulation of BECN1, SQSTM1 and ATG16L1 in human breast cancers, especially in triple-negative subtypes." (PMID 28628113, 2017). "TAM resistant breast cancer cells MCF-7R exhibited higher protein level of Beclin 1 along with increased HER2 than MCF-7 cells." (PMID 28881721, 2017). "Earlier study also provided evidence on existence of Beclin-1-independent autophagy induced by resveratrol in human breast cancer cells when 3-MA was unable to suppress autophagy." (PMID 28158287, 2017). "We established a tamoxifen resistant ER-positive breast cancer cell subline MCF-7R presenting with higher Beclin 1 and human epidermal growth factor receptor 2(HER2) levels than MCF-7." (PMID 28881721, 2017). "For tumour suppressing function at the initiation stage, ATG Beclin-1 was identified as a tumour suppressor gene as it is mono-allelically deleted in many cases including ovarian cancers (75%), breast cancers (50–70%) and prostate cancers (40%)." (PMID 28320471, 2017). "Compared with the normal mammary tissues, breast cancer tissues showed an obvious reduction in BECN1, ATG16L1 and SQSTM1 levels, whereas OPTN expression was higher in cancer tissues." (PMID 28628113, 2017). "In contrast to previous described role of tumor suppressor, Beclin 1 was reported to be critical for breast cancer cancer stem cell maintenance and tumor development in nude mice." (PMID 28881721, 2017). "To investigate the possible influence of Beclin 1 on TAM resistance in breast cancer, we down-regulated Beclin 1 level of MCF-7 and MCF-7R cells via siRNA transient transfection." (PMID 28881721, 2017). "Breast cancer epithelial cell abundance of Beclin 1 (BCN1), a novel Bcl-2-interacting mammalian autophagy gene, was induced 50% by cyclin D1Stroma." (PMID 29137220, 2017). "Using bioinformatic methods, Beclin 1 mRNA was found to be negatively correlated with overall survival in breast cancer patients receiving TAM treatment." (PMID 28881721, 2017). "To understand the role of autophagy in chemoresistance of breast cancer stem cells, we invalidated BECN1 or BNIP3L expression in XBC4 spheres." (PMID 28445132, 2017). "Our findings thus provide preliminary evidence for the role of EHMT2 in the progression of breast cancer via the suppression of Beclin-1." (PMID 27174920, 2016). "In summary, we have demonstrated a significant role for OHPg/PR-B for Beclin-1 induction and function beginning from the autophagy initiation in breast cancer cells." (PMID 27462784, 2016). "In this present study, we showed that the expression of ATGs was elevated after the inhibition of EHMT2 by BIX in PCR array analysis, and established that the epigenetic transcriptional activation of Beclin-1 occurred in breast cancer cells." (PMID 27174920, 2016). "Although the monoallelic deletion of Beclin-1 has been frequently observed in human breast cancer cell lines and tissues, its epigenetic regulation has not yet been elucidated in detail." (PMID 27174920, 2016). "Treatment of breast cancer cells with BIX removed EHMT2 from the promoter of Beclin-1, leading to the reduction of H3K9me2 and resulting in an open chromatin status." (PMID 27174920, 2016). "In a previous study it was shown that in 56% of breast cancers there was a significant decrease of BECN1 protein expression in cancer cells compared to normal breast epithelial cells." (PMID 26802026, 2016). "Our findings thus indicate that an important tumor-suppressive pathway through Beclin-1 is target of OHPg via its own receptor, actually proposing a distinctive protecting action against breast cancer." (PMID 27462784, 2016). "A high incidence of monoallelic deletion and down-regulation Beclin-1 have been observed in many breast cancer cell lines and in more than 50% of breast tumors; these phenomena are also common in ovarian and prostate cancers." (PMID 27174920, 2016).
breast carcinoma (continued). "A large amount of studies have reported that Beclin 1 expression is reduced in various human cancers, including breast cancers, glioblastomas, ovarian cancers, hepatocellular cancers, esophageal cancers and thyroid cancers compared to normal tissue." (PMID 27683118, 2016). "In this study, we therefore investigated the status of autophagy-associated markers, beclin 1 and LC3, in conjunction with apoptosis-associated markers, TUNEL and M30, in breast cancer tissues." (PMID 26984766, 2016). "This supports the idea that OHPg via PR-B/Bcl-2 axis drives breast cancer cellular senescence which follows an early autophagy mediated by Beclin-1." (PMID 27462784, 2016). "The findings reported herein thus provide some new insights into the regulation of Beclin-1 expression in breast cancer." (PMID 27174920, 2016). "Herein we provide evidence that OHPg/PR-B through Beclin-1 evoke autophagy-senescence transition, in breast cancer cells." (PMID 27462784, 2016). "Consistently, breast cancer tissues were reported to express less beclin 1 than normal breast tissues." (PMID 26984766, 2016). "BIX augmented the levels of endogenous Beclin-1 in a time-dependent manner in the MCF-7 (Beclin-1+/−) and HS578T (Beclin-1+/+) breast cancer cell lines." (PMID 27174920, 2016). "There are several conflicting reports regarding the prognostic value of beclin-1 expression in breast cancer." (PMID 25955408, 2015). "In MCF7 breast cancer cells, resveratrol induced beclin-1 dependent and independent autophagy.Here, we also observed both caspase dependent and independent pathway exists for resveratrol induced cell death in ovarian cancer cells." (PMID 26067645, 2015). "We demonstrated that low expression of beclin-1 in breast cancer cells and high expression of beclin-1 in cancer stromal mesenchymal cells significantly correlates with a poor patient prognosis." (PMID 25955408, 2015). "Our findings are consistent with earlier studies of BECN1 in small cohorts of patients with breast cancer." (PMID 25825707, 2015). "In breast cancer cells, inhibition of autophagy by 3-MA or beclin-1 siRNA potentiated the resensitization of previously antiestrogen resistant breast cancer cells, suggesting a pro-survival role of autophagy in anti-estrogen therapy." (PMID 26666173, 2015). "We are greatly indebted with Dr. Ameeta Kelekar at the University Minnesota for the generous gift of the MCF-7 breast cancer cell lines expressing empty vector and Beclin-1 shRNAs." (PMID 25784654, 2015). "Exogenous expression of beclin-1 in MCF-7 breast cancer cells promoted autophagy, inhibited cell growth, and decreased tumorigenesis in nude mice." (PMID 25955408, 2015). "In contrast, other study showed that Ras-induced expression of Beclin-1 to promote autophagic cell death in MCF-7 breast cancer cells." (PMID 25580621, 2015). "Treatment caused a dose-dependent increase in the total protein levels of LC3A/B, Beclin-1 (Atg6), Atg5, Atg7, and Atg16L1 in BT-474 breast cancer cells." (PMID 25580621, 2015). "Specifically Beclin-1 was knocked down in MCF-7 breast cancer cells and the effect on protein levels was evaluated via Western blot analysis." (PMID 25784654, 2015). "Beclin 1 is a tumor suppressor protein that inhibits the growth of MCF7 human breast carcinoma cells in immunodeficient mice." (PMID 25693418, 2015). "A recent study demonstrated that Beclin 1 and autophagy are required for the tumorigenicity of breast cancer stem-like/progenitor cells." (PMID 25811979, 2015). "Additional studies are in progress to unravel the molecular pathways by which beclin-1 expression or autophagy contribute to the breast cancer stromal microenvironment." (PMID 25955408, 2015). "A comprehensive gene expression analysis was performed on a co-culture of breast cancer cells and mesenchymal stromal cells, that latter of which either expressed beclin-1 or was depleted of beclin-1 by siRNA." (PMID 25955408, 2015).
breast carcinoma (continued). "Another study showed that transfection of Beclin-1 into a transformed breast carcinoma cell line decreased its tumorigenic potential in nude mice." (PMID 24885292, 2014). "Conversion of LC3 I/II and up-regulation of Beclin-1 suggested increased formation of autophagosomes in a time-dependent manner in breast cancer cells." (PMID 25053988, 2014). "Since intracellular ROS levels are closely linked to the regulation of autophagy, we followed the autophagy biomarkers beclin-1, LC-3, Atg7 and Atg5 protein levels in breast cancer cells in which the CYP2E1 was either ectopically expressed or silenced." (PMID 24207099, 2013). "An earlier study showed that transfection of breast cancer cells that lack detectable endogenous Beclin-1 protein with Beclin-1 gene inhibited cell growth and tumor clonigenicity in vitro and in vivo." (PMID 23765161, 2013). "Beclin 1 was found to be monoallelically deleted in 40% of sporadic human breast cancers, establishing the first functional link between autophagy and cancer." (PMID 23840208, 2013). "Inhibition of BCL-2 expression has also been reported to elevate Beclin 1 levels and result in the death of breast cancer cells." (PMID 23840208, 2013). "It has been reported that overexpression of Beclin 1 activates autophagy and reduces the tumorigenetic potential of breast cancer cells." (PMID 23270461, 2012). "In MCF7 breast carcinoma cells the expression of Beclin 1 protein decreases below detectable levels." (PMID 22540380, 2012). "A mutation in FYVE-CENT (R1945Q) associated with breast cancer abolished the interaction between FYVE-CENT and Beclin 1, and reduced the localization of these proteins at the intercellular bridge during cytokinesis." (PMID 21455500, 2011). "Altogether, the associations to clinical parameters strengthen the links between FYVE-CENT, Beclin 1 and breast cancer biology." (PMID 21455500, 2011). "In conclusion, our studies confirmed that down-regulation of beclin 1 expression is present in breast cancer." (PMID 20230646, 2010). "As a whole, down-regulated expression of beclin 1 was found in 14 out of 20 (70%) of the breast cancer tissues." (PMID 20230646, 2010). "It has been reported that reduced levels of beclin 1 expression and mono-allelic deletion were observed in human breast cancer cell lines and tissues." (PMID 20230646, 2010). "Ceramide, camptothecin, and EB1089 induce autophagic cell death in breast cancer cells and all of these agents increase Beclin 1 protein expression." (PMID 21129193, 2010). "Beclin 1 is a tumour suppressor, and it inhibits breast cancer growth." (PMID 40650785, 2025). "Lower Beclin-1 expression is observed in almost 70% of breast cancer specimens." (PMID 39858015, 2025). "In addition, it triggered programmed cell death in breast cancer cells by epigenetic alterations by upregulating Beclin 1 and LC3B while downregulating p62 and mTOR protein expression." (PMID 38563878, 2024). "Another study revealed that miR-199a-5p overexpression in breast cancer cells could upregulate the expression of autophagy-related genes BECN1 and DRAM1, consequently activating cellular autophagy." (PMID 38315272, 2024). "Indeed, co-culturing adipocytes with breast cancer cells resulted in remarkably low expression of adipogenic markers and BECN1." (PMID 38744820, 2024). "Multiple studies have revealed that Beclin-1 gene plays a multifaceted role in breast cancer." (PMID 38315272, 2024). "Beclin-1 also demonstrated the ability to restrain the invasive metastasis of breast cancer cells." (PMID 38315272, 2024). "Moreover, given its proximity to the chromosome, Beclin-1 is often subjected to common deletion along with the breast cancer susceptibility gene 1 (BRCA1), making Beclin-1 deletion more likely to induce breast cancer." (PMID 38315272, 2024).
breast carcinoma (continued). "Therefore, we evaluated the impact of beclin 1-mediated autophagy on reduced drug sensitivity in breast cancer chemoresistance attributed to the reduction in miR-30a caused by HIF-1α through the loss of miR-622." (PMID 38339408, 2024). "Beclin-1 and LC3 are overexpressed in breast cancers and are associated with poor survival in TNBC patients, suggesting that targeting FOXM1 may suppress the tumor-promoting autophagic process." (PMID 39594778, 2024). "Next, we co-injected WT or Becn1 KO imSVCs and breast cancer cells (4T1) into the mouse flanks." (PMID 38744820, 2024). "Most of these studies focused on beclin-1 as autophagy-related target of mir-30a, but here our results showed that the inhibitory effect of mir-30a goes behind beclin-1 and there are several autophagy-related genes which are targeted by mir-30a in breast cancer." (PMID 39716374, 2024). "In human breast cancer cells, S100a9 could promote autophagy by upregulating the Beclin-1 and promoting the formation of Atg12-Atg5 and lysosome activation, thereby inducing cell death." (PMID 37723445, 2023). "In human breast cancer cells, S100a9 could promote autophagy and induce cell death by upregulating the expression of Beclin-1, as well as by promoting the formation of Atg12-Atg5 and lysosomal activation." (PMID 37723445, 2023). "In addition, monoallelic deletion of Becn1 in FVB/N mice results in the development of mammary tumors after parity." (PMID 37190065, 2023). "Interestingly, Bcl-2 is overexpressed in breast cancer and its pro-survival and pro-tumorigenic functions in breast cancer are correlated to its capacity to inhibit autophagy by binding to Beclin-1." (PMID 35884904, 2022). "Another investigation provided evidence that blocking ATG6 (beclin-1) could enhance the efficacy of estrogen receptor (ER)-positive breast cancer cells." (PMID 35814435, 2022). "BECN1 knock-in mutation also reduces amyloid oligomers and improves cognitive function in a mice model of Alzheimer’s disease, and reduces HER2-driven breast cancer tumorigenesis in mice." (PMID 35832792, 2022). "Similarly, tumor progression in breast cancer is related to low expression of miR-124-3p that controls autophagy induction by means of Beclin-1." (PMID 35309939, 2022). "Previous studies have suggested that DNA methyltransferase could modulate the increase in methylation in the promoter region of beclin 1 in breast cancer." (PMID 36166308, 2022). "This supports the importance of Beclin-1 (and autophagy) in breast cancer development." (PMID 35884904, 2022). "However, it is essential to specify that the Beclin-1 gene is on a chromosomal region that is frequently deleted in approximately 50% of sporadic breast carcinomas." (PMID 35884904, 2022). "In addition, overexpression of the Beclin-1 gene has been reported to suppress tumorigenesis in MCF-7 human breast cancer cells." (PMID 36104717, 2022). "BRCA1 mutations dramatically increase the risk of developing breast cancer, which suggests the loss of Beclin-1 is not likely to be the primary cause of breast cancer." (PMID 35884904, 2022). "Furthermore, some studies reported that Beclin 1 independent autophagy induction through Bcl-2 inhibitors, is observed in diseases like breast cancer and colorectal cancer by ABT-199 and obatoclax, respectively." (PMID 36309485, 2022). "Beclin-1 overexpression in breast cancer cells reduced cell proliferation and tumorigenesis." (PMID 35884904, 2022). "It has been reported that Bcl-2 antagonized the autophagy pathway, subverted the internal protein quality and genome stability and promoted the growth of breast cancer cells, indicating that Beclin 1 and Bcl-2 can be served as attractive targets for cancer therapy." (PMID 36676047, 2022).